MIR199A1 (microRNA 199a-1)
Synonyms: hsa-mir-199a-1; MIR-199-s; MIRN199A1; mir-199a-1
Gene: MicroRNA gene on chromosome 19 (10,817,426 to 10,817,496, reverse strand). Ensembl gene ENSG00000207752.
Gene Ontology:
Biological process: miRNA-mediated post-transcriptional gene silencing
Cellular component: RISC complex
Homologues: Orthologues: chimpanzee ptr-mir-199a-1 (100% identical), macaque mml-mir-199a-2 (99% identical), pig ssc-mir-199a-2 (97% identical), guinea pig MIR199A1 (92% identical), mouse Mir199a-1 (90% identical), zebrafish mir199-2a (80% identical), tropical clawed frog xtr-mir-199b (68% identical). Paralogues in human: MIR199B (83% identical), MIR199A2 (82% identical).